HIF1A (hypoxia inducible factor 1 subunit alpha)
Diseases named in the same sentence as HIF1A in open-access papers (continued):
Sharing a sentence is not in itself a finding about the gene and the disease.
tumor (continued). "Thus, down-regulation of HIF-1α and VEGF expression by alleviating tumor hypoxia would inhibit tumor progression." (PMID 29461122, 2018). "However, the tumor cell lines HT29 and B16F10 exhibited higher protein expression levels of NF-κB, HIF-1α or CREB than normal cell lines, including HUVECs and HEK293 and Balb3T3 cells." (PMID 29703163, 2018). "Subsequent RNA-seq and western blot revealed that the expression of HIF1ɑ was closely correlated with HIF1A duplication in tumor tissues, whereas gene expression of CDKN2A and PALB2 was not significantly changed (fold-change < 2)." (PMID 30062063, 2018). "Interestingly, a macrophage-targeted HIF-1α and HIF-2α knockout resulted in delayed tumour progression in models of breast tumour, fibrosarcoma and colitis-associated colon carcinoma." (PMID 30301842, 2018). "HIF-1α staining frequency in vital tumor tissue was low with a median of 0%, therefore we did not include a dichotomized analysis in our study." (PMID 30129426, 2018). "HIF-1α-staining verified hypoxia in central HT1080 and A431 tumor areas, where vessel wall damage by rhodocetin-αβ was especially prominent, and abundant composite/ATV/VM vessels were just partially EC-lined (arrows) or even completely devoid of ECs (open arrows)." (PMID 29854288, 2018). "However, patients with low levels of HIF-1α protein and a high content of EGFR protein in the tumor had a three-fold better survival compared to patients without such constellation regarding the protein level of HIF-1α and EGFR." (PMID 30513863, 2018). "Expression of EIF3C did not alter proliferation and expression of other tumor progressive genes such as HIF1A, TGFβ1 and VEGF, but reduced cell migration in HCC cells." (PMID 29568350, 2018). "Unlike its role in tumor, HIF-1α fails to induce proangiogenic response by using a transgenic model of overexpression of HIF-1α." (PMID 30622603, 2018). "Several studies have demonstrated that HIF-1α, AP-1, and VEGF-A may be related to tumor microvessel formation and can promote tumor angiogenesis." (PMID 30250188, 2018). "Our results demonstrated that the ERK/p70S6K/HIF-1α signalling pathway may be partially responsible for the UBE2CP3-induced accumulation of VEGFA and leads to tumor cell-mediated angiogenesis." (PMID 29866133, 2018). "We isolated 956 EpCAM+ cells and observed 762 negative, 139 low, and 55 high HIF1α protein-positive cells from the tumor." (PMID 30389926, 2018). "HIF-1α is able to recruit monocytes and macrophages by promoting chemical chemokine 2 (CCL2) secretion, which accelerates the activation of PSCs and enhances tumor progression." (PMID 30455857, 2018). "Silencing HIF-1α, HIF-2α or combined HIF-1α and HIF-2α had a profound effect on tumor growth." (PMID 29632647, 2018). "Considering only patients with no recurrence after the primary tumor resection, HIF-1α mRNA (RR = 0.8, p = 0.57) (data not shown) levels had no impact on survival in the univariate Cox’s regression hazard analysis." (PMID 30513863, 2018). "Furthermore, deguelin inhibits tumor cell propagation and malignant transformation through p27-cyclinE-pRb-E2F1 cell cycle control and HIF-1α-VEGF anti-angiogenic pathways." (PMID 29416603, 2018). "Immunohistochemistry (IHC) analysis showed that HIF-1α expression was greatly decreased in both Fuco-MnO2-NP and PAH-MnO2-NP cotreated groups, suggesting that MnO2-NPs may alleviate tumor hypoxia in vivo as well as in vitro." (PMID 30558324, 2018). "Interestingly, hypoxia-induced HIF-1α is able to increase the expression of costimulatory receptors, such as CD137, on tumor-infiltrating T cells." (PMID 30076128, 2018). "As HIF1α is central to various preneoplastic and neoplastic diseases, it is not surprising therefore that HIF1α has been identified as a crucial molecular mediator during Mtb infection in humans and mice." (PMID 30374347, 2018). "We next examined HIF-1α levels in vitro and in vivo and a role of ABCG1 in tumor HIF-1α level." (PMID 30364132, 2018).
tumor (continued). "In this study, we found by multivariate Cox’s regression analysis that both low EGFR and low HIF-1α mRNA levels are independent negative prognostic markers for tumor-specific survival in analyzed STS patients." (PMID 30513863, 2018). "Additionally, TRPC5-mediated Ca2+ entry promoted transcription of HIF-1α gene, thereby boosting VEGF release and enhancing tumor angiogenesis." (PMID 29324706, 2018). "However, HIF-1α and HIF-2α expression was examined in only 85 and 78 tumor tissues, respectively, because some tissue specimens were insufficient for IHC assays of all target proteins." (PMID 29357946, 2018). "While HIF-1α is known to promote cell arrest via mTORC1 repression and other mechanisms, HIF-2α can activate mTORC1 to induce cell proliferation and growth in a number of cell types and organs, for example, tumour cells or the lung epithelium." (PMID 29671738, 2018). "In the first ones it directly abrogates VEGF induced proliferative effect, while in tumor cells the nonoate inhibits HIF-1α dependent VEGF upregulation." (PMID 29568362, 2018). "A study in thyroid cancer cells showed that depletion of hypoxia-inducible factor-1α (HIF-1α) resulted in a decrease in WWP2 expression, suggesting a possible mechanism by which hypoxic conditions in the tumor may result in increased WWP2 expression." (PMID 29954076, 2018). "Accordingly, tumor cells xenografted with TRAP1-expressing Saos-2 cells had detectable levels of HIF1α, whereas HIF1α downmodulation prevented focus-forming in TRAP1-expressing tumor cells and in mouse embryonic fibroblasts (MEFs) transfected with a TRAP1-expressing construct." (PMID 29621137, 2018). "Tumor cells secrete lactate into the TME, which activates macrophage recruitment, induces their functional polarization into TAMs, and stimulates vascular endothelial growth factor (VEGF) production in TAMs through HIF-1α." (PMID 30248111, 2018). "HIF-1α increased by TSA-mediated acetylation enhances VEGF expression with HRE, which might be the effort for tumor cells to be survived in the environment with cell death signal." (PMID 29416751, 2018). "HIF-1α, induced by the hypoxic microenvironment, generated during anti-angiogenic therapy stimulates β1 integrin expression, which interacts with c-MET signaling and results in an enhancement of tumor cell invasiveness." (PMID 29670046, 2018). "The transcriptional activity of c-myc and the stabilization of hypoxia inducible factor 1 alpha (HIF1α) in cancer cells enhance the expressions of most glycolytic enzyme genes, including lactate dehydrogenase-A (LDHA) and GLUT1, which in turn increase tumor aggressiveness and lead to poor survival." (PMID 30258444, 2018). "Some research has identified that the loss of HKII led to a reduced activation of ERK phosphorylation in tumor cells, and other studies indicated that the activation of ERK can promote the HIF-1α translation by phosphorylating MAP kinase interacting kinase (MNK)." (PMID 29682563, 2018). "The need for more oxygen supply in hypoxic tumors activates hypoxia-inducible factor 1 alpha subunit (HIF1A) to produce vascular endothelial growth factor (VEGF) which in turn triggers angiogenesis to increase oxygen supply and sustain tumor’s survival and growth." (PMID 29311558, 2018). "Not surprisingly, several cytokines activate the HIF-1α pathway, actually evoking a hypoxic-like response in the tumor mass." (PMID 29996493, 2018). "This phenotype was observed without HIF-1α stabilization and activation and conferred cell resistance to apoptosis induction, as previously observed with tumor cells grown in hypoxia." (PMID 29596470, 2018). "OL suppressed HFD-induced tumor growth by reducing the expression of angiogenesis (CD31, VE-cadherin, VEGF-A, and VEGFR2), lymphangiogenesis (LYVE-1, VEGF-C, VEGF-D, and VEGFR3), and hypoxia markers (HIF-1α and GLUT-1)." (PMID 30340320, 2018).
tumor (continued). "HIF-1α is ubiquitinated and degraded under abundant oxygen environment, while hypoxia enables HIF-1α translocation to the nucleus and eventually promotes the adaption of tumor cells to hypoxic microenvironment which often occurs in a wide range of cancers." (PMID 30456206, 2018). "Compared to sham-treated animals, intratumoral Hif1-α protein levels were lower in the combination treatment group and tumor sizes were not significantly different." (PMID 29254140, 2017). "Interestingly, in mice miR-21 has also been shown to induce tumor angiogenesis by targeting PTEN and activating AKT and ERK1/2 signaling pathways, which then in turn enhances VEGF and hypoxia-inducible factor 1-alpha (HIF1A) expression." (PMID 29326752, 2017). "Accordingly, we measured the proliferation, migration, RhoA activation, the mRNA and protein levels of hypoxia inducible factor-1alpha (HIF-1α) and three small G-proteins, Rac1, cdc42 and RhoA in a panel of five human tumor cell lines under normoxic and hypoxic conditions." (PMID 28562340, 2017). "In an effort to develop an efficient strategy for AML treatment, we found that BA could slightly suppress tumor growth through ROS generation and AHR activation with subsequent HIF1α suppression in THP1 cells." (PMID 29212263, 2017). "Moreover, after oral administration of ETAKG to a mouse xenograft tumour model, increased levels of AKG within the tumour tissues were observed, as well as decreased levels of HIF-1α, and reduced glucose metabolism." (PMID 27326424, 2017). "Response to androgen deprivation therapy in mice with CWR22RV1 xenografts, suggests that AR may regulate HIF-1α levels, as expression of both AR and HIF-1α target genes were affected even outside of hypoxic tumor areas." (PMID 28394264, 2017). "In contrast, NK cell depletion in tumour-bearing HIF-1α KO mice led to a discrete rescue of tumour growth, without impact on the vascular phenotype, tumour hypoxia, or tumour cell death." (PMID 29150606, 2017). "Heteromorphism was not obvious in the transplantation tumor cells of HIF-1α/siRNA group and vascular systems were sparse in its tissues, but in SCR/siRNA group heteromorphism was obvious and vascular systems were increased." (PMID 28523034, 2017). "To determine whether PI3K/AKT signalling accounts for the HIF-1α-mediated GLUT1 expression in SqCC, we analysed activities of AKT and its downstream signalling pathways as well as HIF-1α expression in KL SqCC and ADC tumours." (PMID 28548087, 2017). "High levels of HIF-1α protein and mRNA have been observed in PCa tissues and cell lines, and our data demonstrate that HIF-N (nuclear HIF-1α expression, the functional state) correlates significantly with TNM stage, Gleason score, tumor progression and poor survival (both DSS and PFS)." (PMID 29137361, 2017). "We next examined HIF1α and BAF180 protein expression in a ccRCC tumor tissue microarray." (PMID 28092369, 2017). "Tumor-associated hypoxia is known to upregulate hypoxia inducible factor 1-α (HIF1-α), transcribe stromal cell-derived factor 1α (SDF-1α), and promote secretion of proangiogenic factors to recruit CXCR4+ bone marrow-derived cells (BMDCs) in the tumor milieu." (PMID 29062041, 2017). "Another key element of angiogenesis in tumors is the transcription factor hypoxia-inducible factor 1 (HIF-1) which under hypoxic condition characteristic for the center of tumor, increases the transcription of VEGF, and furthermore, both HIF-1α and VEGF expression can be stimulated by ROS." (PMID 28626501, 2017). "A tendency towards an increased expression of HIF-1α was observed in the PC group with an increased tumor stage, although this was not statistically significant." (PMID 29084538, 2017). "Global 5mC methylation along with HIF-1α levels were monitored in vitro and in vivo during the course of tumor regression upon hypoxia reversal, using human cervical cancer (HeLa) and murine bladder cancer (MB49) tumor models." (PMID 28839175, 2017).
tumor (continued). "This once more indicates that impaired tumour growth in HIF-1α KO mice does not primarily rely on NK cell cytotoxicity." (PMID 29150606, 2017). "The present study investigated, by immunohistochemical analysis, the protein expression of HIF-1α, PDK1, PHD3, PFKFB4, and VEGFA, five genes extensively modulated in hypoxic conditions, the typical state of tumor microenvironment strictly connected with cancer cells growth and propagation." (PMID 29117193, 2017). "In line with these in vitro data, xenograft tumor-take and growth were not significantly affected by repressed HIF1A expression." (PMID 28430666, 2017). "In tumor cells, HK2 plays a critical role at the focus point of two central pathways of glycolysis control – c-Myc and hypoxia-inducible factor 1-alpha (HIF1α) pathways to provide tumor cells with energy and metabolic compounds for the synthesis of nucleotides and proteins." (PMID 28415659, 2017). "Ethanol markedly enhanced arsenic-induced tumor angiogenesis which was attributed to intracellular ROS generation, NADPH oxidase activation, and activation of PI3K/Akt and hypoxia-inducible factor 1 alpha (HIF-1α)." (PMID 28538665, 2017). "HIF-1α and HIF-2α are often overexpressed in solid tumors and tumor-derived cell lines." (PMID 27121066, 2017). "Moreover, HIF-1α AS-ODNs and GLUT-1 AS-ODNs had synergistic interaction effects with 10 Gy X-ray irradiation on increasing tumor cells AI and necrosis, and decreasing MVD." (PMID 28410229, 2017). "Yet, such alterations of the immune infiltrate are believed to rather slow down tumour growth, and therefore are unlikely to contribute to tumour growth promotion in NK cell-depleted tumours from HIF-1α KO." (PMID 29150606, 2017). "It is becoming clear that HIF-1α expression alone is not a reliable marker of tumor response to hypoxia." (PMID 29312568, 2017). "Taking also this observation into account, the tumor take was still not significantly affected by the HIF1A expression status." (PMID 28430666, 2017). "Thus, elevated HIF-1α induces the elevation of multiple target genes, e.g. VEGF, CA9 and MMP2, eventually resulting in aberrant proliferation, invasion and tumor progression." (PMID 29100347, 2017). "Moreover, hypoxia indices (HIF-1α and GLUT-1) were increased in the tumor tissues of HFD-fed mice, and were decreased in the tumor tissues of OL-fed mice." (PMID 28410190, 2017). "Our results confirmed that ADM is an upstream molecule of HIF-1α/VEGF, so we suppose ADM may be involved in the regulation of other angiogenic “classic” factors to promote tumor angiogenesis." (PMID 28091613, 2017). "During responsiveness to Bev, probably because oxygen demand by the tumor decreases, hypoxic markers (HIF-1α and CA9) and the marker for stem cell and vascular proliferation (nestin) are decreased, suggesting that tumor oxygenation is preserved; thus, VEGF and its receptors are relatively reduced." (PMID 29262608, 2017). "We showed that miR-1 inhibited tumor proliferation by suppression of glycolysis and negative regulation of Smad3 activity and HIF-1α expression." (PMID 28471448, 2017). "HIF-1α and CA9 expression was attenuated in the tumor exposed to DT." (PMID 28410215, 2017). "Additionally, the western blot indicated that the protein level of HIF-1α, CD73 and A2AR was upregulated in 2cKO tumor bearing mice as compared with the wild type mice." (PMID 28592285, 2017). "Additionally, we posit that investigational drugs targeting HIF-1α catabolism, ROS inhibition, GPR91 stimulation, PHD activity promotion and tumor-promoting inflammation should be developed to improve clinical treatment." (PMID 28881853, 2017). "In solid tumors, tumor cells produce transcription factors like NF-κB, signal transducer and activator of transcription 3 (STAT3), and hypoxia-inducible factor 1α (HIF-1α), all of which have a profound effect on the recruitment, differentiation, and maturation of infiltrating leukocytes." (PMID 28471401, 2017).
tumor (continued). "This indicates that, in contrast to splenic NK cells sVEGFR1 production in tumour-infiltrating NK cells is induced by salvage pathways and does not solely rely on HIF-1α expression." (PMID 29150606, 2017). "NK cell depletion was associated with an increase in CD8 T cell numbers and a decrease in F4/80 macrophages, but these changes are unlikely to explain increased tumour volumes in NK cell-depleted HIF-1α KO mice." (PMID 29150606, 2017). "pVHL-mediated tumor suppression is also nullified with forced-expression of HIF-2α (but not HIF-1α)." (PMID 28257457, 2017). "The expression levels of miRNAs miR-99a, 99b, 100; 199a; 106a; 106b; 29a; 29b; 29c; 126; 200a, 200b and their respective target genes: mTOR, HIF1-α, VHL, PDGF, VEGF, VEGFR1 and VEGFR2 were analyzed using qRT-PCR in tumor tissue samples from 56 patients with ccRCC." (PMID 29202733, 2017). "Directed tumor cell killing by T cells is not affected by the loss of T cell VEGF-A, indicating that this aspect of HIF-1α function is not VEGF-A dependent." (PMID 29136509, 2017). "Immunofluorescence analysis of tumor sections showed that CUR significantly decreased HIF-1α expression compared to that of the untreated group, which indicated CUR could inhibit tumor angiogenesis." (PMID 28881600, 2017). "This was accompanied by the upregulation of the hypoxia inducible factors HIF1α and HIF2α during BIX-01294 treatment even in normoxia that may facilitate the tumor suppressive effects of BIX-01294." (PMID 29145444, 2017). "A large body of data indicates that HIF-1α and VEGF contribute to tumour angiogenesis." (PMID 29072683, 2017). "In summary, our study discloses that hypoxia/HIF-1α induces ENTPD2 in cancer cells to increase the extracellular level of 5′-AMP, which prevents M-MDSCs from maturation, therefore maintaining MDSC undifferentiated in the tumor stroma." (PMID 28894087, 2017). "The growth of cancer cells and VEGF expression, which controls angiogenesis, has been observed to be regulated by HIF-1α, whereas IL-8 does not affect tumor growth or VEGF expression." (PMID 28053598, 2017). "The in vivo metastasis assays showed that CoCl2, applied for induction of HIF-1α stabilization, significantly increased the liver colonization capacity of HT168-M1 cells, while the inhibition of HIF proteins decreased the number of tumor foci in the liver." (PMID 28562340, 2017). "HIF-1α is known to enhance MDSC differentiation and effector functions in tumor immunology." (PMID 28892492, 2017). "No genotype-specific differences in infiltration of other immune cell subsets were detectable, further indicating that impaired tumour growth in HIF-1α KO mice does not primarily rely on NK cell cytotoxicity." (PMID 29150606, 2017). "One major issue of TACE was contributed by the over-expression of VEGF and HIF-1α which result in tumor progression, invasion and metastasis.SOR is a multikinase inhibitor which is able to suppress tumor cell proliferation by targeting theVEGF receptor and/or the PDGF receptor." (PMID 27705924, 2017). "Emodin and rhein also decreased the expression of HIF-1α, HK-II and PFK-1 in tumor grafts." (PMID 29152137, 2017). "In this study, we show that HIF-1α mRNA is a functionally relevant target of miR-199a-5p, the downregulation of which contributes to the oncogenic high level of HIF-1α in Pca, as well as tumor progression and unfavorable patient survival." (PMID 29137361, 2017). "IL1-β also regulates HIF-1α protein, involving an inflammatory signaling pathway to NF-ĸB and COX-2, resulting in the upregulation of VEGF (vascular endothelial growth factor), a potent angiogenic factor needed for metastasis and for tumor growth." (PMID 28785138, 2017).